LYZ (lysozyme)
Diseases named in the same sentence as LYZ in open-access papers (continued):
Sharing a sentence is not in itself a finding about the gene and the disease.
malaria (3 papers, 2012 to 2024). Malaria is a serious and sometimes fatal disease caused by a parasite that commonly infects a certain type of mosquito which feeds on humans. "Thus, at the moment an invivo involvement of the full digestive vacuole as a causative agent of the enhanced lysozyme levels found in plasma of patients with malaria cannot be excluded." (PMID 22724024, 2012). "Collectively, the findings of the present work support the hypothesis suggesting a potential role for lysozyme as an early marker of disease severity in falciparum malaria, and might be useful in order to design in the future specific diagnostic approaches for severe malaria." (PMID 22724024, 2012). "While other report evaluated activation of polymorphonuclear cells and observed elevated levels of myeloperoxidase, lysozyme and lipocalin in patients with severe malaria, the involvement of neutrophils in malaria pathogenesis has been poorly investigated." (PMID 22745844, 2012). "Incorporation of additional neutrophil activation markers, e.g., myeloperoxidase, lysozyme and neutrophil-specific granule proteins, and pro-inflammatory chemokines may further elucidate involvement of neutrophil activation in knowlesi malaria pathogenesis." (PMID 39150978, 2024). "In humans, plasma levels of lysozyme, along with those of mieloperoxidase and lipocalin, correlated significantly to degree of parasitaemia, suggesting that the levels of these molecules might be good markers of severe malaria." (PMID 22724024, 2012).
malnutrition (3 papers, 2021 to 2023). Inadequate nutrition resulting from poor diet, malabsorption, or abnormal nutrient distribution. "A few studies have indicated that IgA, IgG and lysozyme levels are significantly decreased in the breast milk of mothers with malnutrition compared with mothers of a healthy nutritional status." (PMID 34444830, 2021).
oral candidiasis (3 papers, 2014 to 2023). Infection of the mucosal lining of the mouth with the fungus Candida albicans. "The dental biofilm promotes the adhesion of Candida albicans and reduces the production of antimicrobial proteins such as lysozyme and lactoferrin, reducing the antimicrobial properties of saliva and predisposing the subject to oral candidiasis." (PMID 37238357, 2023). "Human whole saliva contains several antibiotics such as lysozyme, lactoferrin, peroxidases, and salivary immunoglobulin A. Many studies have pointed to an association between oral candidiasis and constant hyposalivation." (PMID 24979710, 2014).
osteoporosis (3 papers, 2023 to 2024). A condition of reduced bone mass, with decreased cortical thickness and a decrease in the number and size of the trabeculae of cancellous bone (but normal chemical composition), resulting in increased fracture incidence. "For another, it had been proved that ASP could ameliorate osteoporosis by altering gut microbiome via microbial protein lysozyme and the immune system in estrogen-deficient rats." (PMID 39449745, 2024). "ACP increases LYZ expression by maintaining the number of Paneth cells and ameliorates osteoporosis by controlling the inflammatory response." (PMID 37916145, 2023). "The results of our research indicate a significant increase in the concentration of lysozyme in the group of patients suffering from osteoporosis, regardless of taking AR drugs." (PMID 36901300, 2023).
otitis media (3 papers, 2008 to 2021). Inflammation of the anatomical structures of the middle ear, which is most often caused by an infectious process. "In addition to our prior study showing that lysozyme deficiency inhibits pneumococcal clearance from the middle ear cavity, MyD88 deficiency is known to delay resolution of NTHi-induced otitis media." (PMID 24625812, 2014). "Lysozyme and other antimicrobial proteins and peptides were investigated by the same research team, and their use was suggested for the treatment of otitis media and paranasal sinusitis." (PMID 34943746, 2021). "The authors suggested that exogeneous lysozyme can be used as an adjuvant therapeutic agent for otitis media." (PMID 34943746, 2021). "We suggest a possibility of the exogenous lysozyme as an adjuvant therapeutic agent for otitis media, but further studies are necessary." (PMID 18842154, 2008).
renal fibrosis (3 papers, 2020 to 2025). A final common manifestation of a wide variety of chronic kidney diseases characterized by glomerulosclerosis and tubulointerstitial fibrosis. "For example, lysozyme has been identified as a key regulatory factor in mediating renal fibrosis in diabetic nephropathy, with Lyz overexpression promoting the release of glucose-induced fibrosis-related cytokines." (PMID 40787440, 2025).
respiratory infections (3 papers, 2016 to 2025). "EBBC ‘s broad-spectrum virucidal activity is promising for the prevention of respiratory infections, particularly given lysozyme’s established efficacy against various strains of influenza A viruses and even avian flu viruses like H5N1, H5N6, and H7N1." (PMID 41306594, 2025).
uveitis (3 papers, 2021 to 2025). An inflammatory process affecting a part of or the entire uvea. "Nevertheless, in our daily experience as a reference center of uveitis patients, lysozyme is rarely ordered by general ophthalmologists in the investigation of OS." (PMID 33805490, 2021).
xerostomia (3 papers, 2020 to 2024). Dryness of the mouth resulting from reduced salivary secretion. "Lysozyme is effective against C. albicans and various oral Gram-positive bacteria and may be particularly useful as a treatment in patients with reduced saliva lysozyme concentration, such as children with chronic tonsillitis and patients with oral mucositis or xerostomia (dry mouth)." (PMID 32498237, 2020). "BioXtra gel containing lysozyme was studied in a non-randomized trial among 58 patients with head and neck cancer where improved xerostomia symptom score after 2 weeks use was reported." (PMID 33175253, 2021).
abdominal aortic aneurysm (2 papers, 2021 to 2025). Enlargement and ballooning of the vessel that supplies arterial blood to the abdomen, pelvis and legs. "Finally, in CaCl2-induced rodent abdominal aortic aneurysm (AAA) models, we found that the 12:1 mixture of GS-Re and lysozyme slowed down AAA progression and reversed phenotype transformation of VSMCs." (PMID 35004822, 2021).
acute pancreatitis (2 papers, 2023 to 2025). An acute inflammatory process that leads to necrosis of the pancreatic parenchyma. "In mice, the recovery of functional Paneth cells through α-defensin or lysozyme supplementation can effectively alleviate intestinal injury caused by dextran sulfate sodium (DSS) treatment, Helicobacter hepaticus infection, or acute pancreatitis." (PMID 37582766, 2023). "Furthermore, exogenous lysozyme supplementation can not only alleviate the severity of acute pancreatitis (AP) and its intestinal complications by regulating the gut-pancreas axis, but also indirectly protect lung health through the gut-lung axis, reducing lung injury caused by oxygen excess." (PMID 40381082, 2025).
anaphylaxis (2 papers, 2015 to 2025). An acute hypersensitivity reaction that occurs from exposure to an allergen. "Severe reactions (e.g., anaphylaxis) correlated with higher lysozyme-sIgE levels (>7 kU/L)." (PMID 41561179, 2025). "In this case, the subjects sensitized to lysozyme tolerated this protein taken orally, as shown by DBPCFC in two subjects having anaphylaxis at inhalation but no reaction to cheese or wine treated with lysozyme (Restani, unpublished data)." (PMID 26197307, 2015).
anemia (2 papers, 2021 to 2023). A reduction in the number of red blood cells, the amount of hemoglobin, and/or the volume of packed red blood cells. "Regarding the systemic response, challenged fish presented neutrophilia, monocytosis, signs of anemia, and a decrease of bactericidal and lysozyme activities in plasma." (PMID 37731496, 2023).
Autoimmunity (2 papers, 2019 to 2024). The occurrence of an immune reaction against the organism's own cells or tissues. "Innate immunity, which encompasses elements, such as lysozyme, immunoglobulin, cytokines, transfer factors, complements, and lymphocytes, plays a pivotal role in the initial defence and autoimmunity of fish." (PMID 38623154, 2024). "Moreover, lysozyme was significantly up-regulated, which will be very helpful to overcome external adverse factors and provide favorable conditions for its autoimmunity." (PMID 31835398, 2019).
avian influenza (2 papers, 2020 to 2025). Infection of domestic and wild fowl and other birds with influenza A virus. "The levels of immunoglobulin G, acid α-naphthylacetate esterase positive ratios and lymphocyte proliferation on d 21 and 42 as well as lysozyme activity and avian influenza antibody H5N1 titer on d 21 decreased (p<0.05) by the stale maize." (PMID 31480160, 2020). "The decreased IgG, ADAE+ and lymphocyte proliferation, lysozyme activity and avian influenza antibody H5N1 titer may suggest that the stale maize inhibits phagocytes activation and the activity of antibodies, eventually reduces the immunity in broilers." (PMID 31480160, 2020). "For instance, it enhanced macrophage phagocytic activity and antibody titers against avian influenza in quails and increased CD4+ T lymphocyte counts and lysozyme activity." (PMID 41202602, 2025).
bladder cancer (2 papers, 2023 to 2025). "In previous studies on bladder cancer, LYZ has been used as a myeloid cell marker." (PMID 41214597, 2025).
Bovine mastitis (2 papers, 2021 to 2024). INFLAMMATION of the UDDER in cows. "Therefore, historically, a gene therapy strategy to treat bovine mastitis was developed using a mammary-specific vector expressing human lysozyme (hLYZ)." (PMID 39543729, 2024).
celiac disease (2 papers, 2014 to 2019). An autoimmune genetic disorder with an unknown pattern of inheritance that primarily affects the digestive tract. "In coeliac disease, lysozyme is up-regulated in goblet cells, in dilated crypts with mucus-metaplasia, a phenomenon more apparent in the bulbus." (PMID 25437608, 2014). "Only recently, lysozyme was found up-regulated in Barrett’s oesophagitis, chronic gastritis, gluten-induced atrophic duodenitis (coeliac disease), collagenous colitis, lymphocytic colitis, and Crohn’s colitis." (PMID 25437608, 2014).
chronic bronchitis (2 papers, 2006 to 2022). A type of chronic obstructive pulmonary disease characterized by chronic inflammation in the bronchial tree that results in edema, mucus production, obstruction, and reduced airflow to and from the lung alveoli. "Both lysozyme and lactoferrin arise in the lower respiratory tract within the airways and their levels are elevated in association with chronic bronchitis suggesting that lactoferrin and lysozyme may contribute to the modulation of airway inflammation in chronic bronchitis." (PMID 16503962, 2006).
chronic myeloid leukemia (2 papers, 2019 to 2025). "For example, Firkin reported a very high serum lysozyme level of 30–120 μg/mL in chronic myeloid leukemia and myelofibrosis." (PMID 31108965, 2019).
colorectal tumors (2 papers, 2003 to 2021). "Next, we determined the possible association between Notch1 activation and the presence of Paneth cells and LYZ expression in colorectal tumors." (PMID 34831152, 2021). "At least some of these genes have been shown to vary in expression in colorectal tumours, including GST-M1, ALDH and lysozyme, and could play a functional role in the cellular response to camptothecin and its derivatives." (PMID 14583781, 2003).
coronary artery disease (2 papers, 2020 to 2021). "Based on our results, such studies seem well justified, which may also expand to the investigation of cardiorenal syndrome, considering reports associating plasma levels of LYZ to coronary artery disease severity." (PMID 32179759, 2020).
dementia (2 papers, 2011 to 2016). Loss of intellectual abilities interfering with an individual's social and occupational functions. "By contrast, in AD patients a significantly increased level of serum antibodies to both prefibrillar amyloids of Aβ and human lysozyme was found in the early stage of disease and biphasic antibody levels to Aβ peptide oligomers - during the progression of dementia." (PMID 21541339, 2011).
diarrheal disease (2 papers, 2011 to 2013). The condition of having at least three loose or liquid bowel movements each day. "Lysozyme is an antimicrobial protein highly expressed in human milk, but not ruminant milk, and is thought to help protect breastfeeding children against diarrheal diseases." (PMID 23516474, 2013). "Infants fed formula without lysozyme have three times the rate of diarrheal disease." (PMID 21410934, 2011).
fibromyalgia (2 papers, 2019 to 2025). A chronic disorder of unknown etiology characterized by pain, stiffness, and tenderness in the muscles of neck, shoulders, back, hips, arms, and legs. "It was also reported that the activation of TLR4 by lysozyme induced TRIF but not MyD88 and further triggered weak inflammatory cytokine expression and augmented glutamate release, suggesting the existence of a MyD88-independent pathway for nociceptive progression in fibromyalgia." (PMID 41007675, 2025).
Gaucher disease (2 papers, 2012 to 2023). Gaucher disease (GD) is a lysosomal storage disorder encompassing three main forms (types 1, 2 and 3), a fetal form and a variant with cardiac involvement (Gaucher disease - ophthalmoplegia - cardiovascular calcification or Gaucher-like disease). "One early report suggests a modest increase in plasma lysozyme in four adult patients with Gaucher’s disease." (PMID 23094108, 2012). "Alternatively, or additionally, resistance in vivo could be an indirect consequence of GBA deficiency, attributable to induction of microbicidal lysosomal enzymes (e.g., lysozyme) and cytokines (e.g., tumor necrosis factor) characteristic of Gaucher disease." (PMID 36745788, 2023).
glioblastoma (2 papers, 2025). The most malignant astrocytic tumor (WHO grade IV). "According to our research, the LYZ gene is a potential diagnostic biomarker and therapeutic target for glioblastoma (GBM)." (PMID 41514850, 2025). "In glioblastoma, we found immune cells linked to the LYZ gene." (PMID 41514850, 2025). "Furthermore, receiver-operating characteristic (ROC) curve analysis was used to assess the LYZ gene’s diagnostic effectiveness in glioblastoma patients, suggesting that it may be used as a diagnostic biomarker." (PMID 41514850, 2025). "Furthermore, the analysis of signaling pathways revealed that the LYZ gene is linked to several significant signaling pathways in glioblastoma, such as FceRI-mediated NF-kB activation and immunoregulatory interactions between lymphoid and non-lymphoid cells (p < 0.001)." (PMID 41514850, 2025). "This study presents compelling evidence that the LYZ gene represents a novel and promising therapeutic target and diagnostic biomarker for glioblastoma (GBM)." (PMID 41514850, 2025). "The GEO database study, which also revealed a significant overexpression of the LYZ gene in glioblastoma tissues relative to normal controls, further supported this finding." (PMID 41514850, 2025). "The location of the LYZ gene and the cellular heterogeneity of glioblastoma were both revealed by single-cell analysis." (PMID 41514850, 2025). "Among the differentially expressed genes identified, the LYZ gene stood out due to its significant differential expression in glioblastoma tissues and its prognostic relevance." (PMID 41514850, 2025). "Significant variations were seen in the levels of LYZ gene expression throughout the various WHO stages of glioblastoma, with greater expression in more advanced stages." (PMID 41514850, 2025). "We assessed how LYZ gene deletion affected glioblastoma cell migration and invasion in addition to proliferation." (PMID 41514850, 2025). "We looked at the LYZ gene’s mRNA and protein levels in various glioblastoma cell lines to confirm its expression at the cellular level." (PMID 41514850, 2025). "We initially determined which 15 genes had the strongest link with the LYZ gene’s differential expression in order to comprehend the biological roles of the gene in glioblastoma." (PMID 41514850, 2025). "In order to examine the LYZ gene’s functional significance in glioblastoma, we knocked it out using shRNA and evaluated how it affected cell growth." (PMID 41514850, 2025). "The scratch experiment revealed that LYZ gene deletion greatly reduced the capacity of glioblastoma cells to migrate (p < 0.05)." (PMID 41514850, 2025). "Our study aimed to investigate the expression pattern, clinical relevance, and molecular functions of the LYZ gene in glioblastoma." (PMID 41514850, 2025). "This implies that via interacting with leukocytes on the cell surface, the LYZ gene may contribute to the immune response of glioblastoma, potentially affecting the tumor microenvironment and tumor-immune interactions." (PMID 41514850, 2025). "Additionally, to elucidate its functional involvement in tumor biology, we examined the effects of LYZ gene deletion on glioblastoma cell invasion, migration, and proliferation." (PMID 41514850, 2025). "The strong link between these three immune cell types and the expression of the LYZ gene was verified by further correlation analysis, indicating that the LYZ gene may have an impact on the immunological landscape of glioblastoma." (PMID 41514850, 2025). "We also investigated the LYZ gene’s expression pattern in glioblastoma." (PMID 41514850, 2025). "Additionally, the clone formation experiment showed that glioblastoma cells with LYZ gene deletion produced fewer and smaller colonies (p < 0.05), suggesting that the LYZ gene is necessary for glioblastoma cell proliferation." (PMID 41514850, 2025).
glioblastoma (continued). "The selection of the LYZ gene for further investigation was based on its potential to serve as a novel biomarker and therapeutic target, given its differential expression and prognostic significance in glioblastoma." (PMID 41514850, 2025). "The LYZ gene may potentially contribute to glioblastoma cell migration and invasion, as evidenced by the Transwell technique, which showed a decreased invasive capacity of glioblastoma cells in the LYZ-knockout group (p < 0.05)." (PMID 41514850, 2025). "The CCK8 experiment showed that glioblastoma cell lines with LYZ gene knockout had significantly lower proliferation potential than glioblastoma cell lines without LYZ gene knockout (p < 0.05)." (PMID 41514850, 2025).
graft versus host disease (2 papers, 2022 to 2023). An immune system disorder that occurs after allogeneic hematopoietic stem cell transplant and is a reaction of donor immune cells against host tissues. "A range of HDPs, particularly lysozyme and/or lactoferrin, have been shown to be reduced in various types of DED, including SS and non-SS-related DED, evaporative DED, graft versus host disease (GvHD)-related DED, and others." (PMID 35783647, 2022).
head and neck cancer (2 papers, 2021 to 2023). A primary or metastatic malignant neoplasm affecting the head and neck. "Currently detected predominantly using an expensive enzymatic immunoassay (i.e., ELISA test), lysozyme (LYZ) and interleukin-8 (IL-8) have already been shown to be differentially expressed in several disease states of head and neck cancer or infections." (PMID 37960614, 2023).
herpes zoster (2 papers, 2021 to 2025). A common dermal and neurologic disorder caused by reactivation of the varicella-zoster virus that has remained dormant within dorsal root ganglia, often for decades, after the patient's initial exposure to the virus in the form of varicella (chickenpox). "Studies have shown that lysozyme levels in herpes zoster patients are lower in the infected eye compared to the healthy eye, suggesting a link between lysozyme and viral resistance." (PMID 41306594, 2025).